ENSG00000286897 (novel transcript)
Gene: Long non-coding RNA gene on chromosome 15 (58,749,923 to 58,761,004, forward strand). Ensembl gene ENSG00000286897.
Gene Ontology:
Biological process: RNA processing
Cellular component: nucleolus